TCF7L2 (transcription factor 7 like 2)
Diseases named in the same sentence as TCF7L2 in open-access papers (continued):
Sharing a sentence is not in itself a finding about the gene and the disease.
colorectal cancer (continued). "This RNA-binding protein-mediated regulatory mechanism resembles the MIR100HG/hnRNPA2B1/TCF7L2 axis in colorectal cancer, highlighting evolutionarily conserved regulatory logic across diverse biological processes." (PMID 41244234, 2025). "For example, a 3-mm TA harbored one of the highest MB of 6.45, with pathogenic mutational defects in numerous colorectal cancer driver genes (e.g., APC, SOX9, TCF7L2, ASXL1, ERBB3, MAP2K1, and PTPRS)." (PMID 40757636, 2025). "The expression of TCF7L2 was downregulated in breast cancer, colorectal cancer and prostate cancer, while it was upregulated in cholangiocarcinoma, HCC, and gastric cancer." (PMID 39060928, 2024). "Interaction of lncRNA MIR100HG with hnRNPA2B1 promotes m6A-dependent stabilization of transcription factor 7 like 2 (TCF7L2) mRNA and colorectal cancer progression, which is also important for maintaining EMT-related cetuximab resistance." (PMID 38351139, 2024). "HNRNPA2B1 also facilitated the stabilization of TCF7L2 mRNA in an m6A-dependent manner to maintain cetuximab resistance and promote progression of colorectal cancer." (PMID 37215455, 2023). "To shed more light on the importance of TCF7L2 and its role in colorectal cancer, we initially aimed to test the idea that other TCF/LEF family members rescue TCF7L2-deficiency." (PMID 36609428, 2023). "Recent studies have demonstrated that A2B1 interacting with lncRNA MIR100HG stabilizes TCF7L2 mRNA in a m6A-dependent manner to promote colorectal cancer progression." (PMID 38017546, 2023). "It is reported that interaction of lncRNA MIR100HG with hnRNPA2B1 facilitates m6A-dependent stabilization of TCF7L2 mRNA and colorectal cancer progression." (PMID 36894530, 2023). "TCF7L2 is a nuclear transcription factor found to be abnormally expressed in liver, breast and colorectal cancers." (PMID 34753394, 2022). "TCF7L2 protein is a key transcriptional effector of the Wnt/β-catenin signaling pathway and mediates resistance of colorectal cancer to chemoradiation." (PMID 33712565, 2021). "EphrinB2 (EPHB2) expression in a mouse model of colorectal cancer is subject to competing positive regulation by Tcf7l2 and negative regulation by Lef1." (PMID 32403323, 2020). "The salience of resolving a role for phosphorylation in the regulation of transcriptional activation/repression is heightened given the relevance of Tcf7l2 in mediating colorectal cancer outcome due to imbalanced Wnt signalling." (PMID 31829936, 2019). "Sequencing of primary colorectal tumors has identified a gene fusion in approximately 3% of colorectal cancer patients of the VTI1A and TCF7L2 genes, encoding a VTI1A-TCF4 fusion protein containing a truncated TCF4." (PMID 29975781, 2018). "In this study, we explored a global gene expression of colorectal cancer cells transfected with β-catenin siRNAs or a dominant negative form of TCF7L2 (dnTCF7L2), and identified a set of genes down-regulated by Wnt/β-catenin signaling." (PMID 29245969, 2017). "Impaired Wnt signaling pathway plays a crucial role in the development of colorectal cancer through activation of the β-catenin/TCF7L2 complex." (PMID 29245969, 2017). "We relied on the fact that enhancers are enriched in proximity to TSSs, and the clustering of TCF7L2-bound regions occurs within 10 kb of TSSs in colorectal cancer." (PMID 23157480, 2012). "Similar clusters were observed by others in the genes bound by TCF7L2 in a human colorectal cancer cell line." (PMID 23157480, 2012). "Similarly, genetic inhibition of Wnt/β-catenin signaling (by knockout of TCF7L2) caused enhanced tyrosine phosphorylation in 2 additional models, APC-mutant HT29 and β-catenin mutant HCT116 colorectal cancer xenografts." (PMID 38488003, 2024).
colorectal cancer (continued). "The recent investigations have unveiled that HNRNP A2/B1 can specifically interact with m6A, which can interact with MIR100HG and control the activity of the Wnt signaling pathway through recognition of m6A sites on transcription factor-7-like-2 (TCF7L2) mRNA in colorectal cancer." (PMID 39366930, 2024). "TCF7L2 can act as an activator or repressor of Wnt targets depending on cellular context, and has been characterised as a tumour suppressor in colorectal cancer." (PMID 37589076, 2023). "Yet, the TCF7L2 gene carries inactivating mutations in about 10% of colorectal tumors and is non-essential in colorectal cancer (CRC) cell lines." (PMID 36609428, 2023). "Moreover, the lncRNA MIR100HG was found to facilitate TCF7L2 mRNA stability and colorectal cancer progression by interacting with hnRNPA2B1." (PMID 37990246, 2023). "COSMIC fusion VTI1A::TCF7L2, originally identified as an oncogenic fusion in colorectal cancer, was most abundant in stomach, colon, and esophageal carcinoma samples but was also detected in seven individual GTEx normal samples (brain, whole blood, tibial nerve, tibial artery, prostate, and breast)." (PMID 37323575, 2023). "A previous study showed that β-catenin in the nucleus combined with SATB1 could upregulate the transcriptional level of TCF7L2 in colorectal cancer." (PMID 34489551, 2021). "Roles for LEF/TCF proteins has been studied in tissue-culture and animal models of intestinal stem cells and colorectal cancer, which suggested roles for TCF7L2 and TCF7 in normal colorectal tissue, where LEF1 and TCF7L1 are silent, but strong expression in colorectal tumor of LEF1 and TCF7." (PMID 32403323, 2020). "The fact that fusions involving TCF7L2 are highly detectable in colorectal cancers, normal colonic tissue and other normal tissue types, may indicate that these fusions are neither specific to cancer nor to the colon or rectum." (PMID 29975781, 2018). "Recent studies have shown that TCF7L2 may play a role in other diseases besides T2D and colorectal cancer." (PMID 24719615, 2014). "For instance, one of the main variants associated with T2D risk occurs within the genetic region of a known cancer associated locus, namely, TCF7L2 (formerly known as TCF4), where mutations in this genehave been strongly associated with colorectal cancer risk specifically." (PMID 24719615, 2014). "Additionally, pathway analysis of TCF7L2 ChIP-seq data from the colorectal cancer cell line HCT116 demonstrated that the most significant pathways were associated with T2D and cancer." (PMID 24719615, 2014). "The present meta-analysis indicated that there were significantly associations between the TCF7L2 rs7903146 polymorphism and risk of breast, prostate and colon cancers, rather than colorectal cancer, lung cancer, and ovarian cancer." (PMID 23951231, 2013). "In conclusion, the results indicated that there was a significantly association between TCF7L2 rs7903146 polymorphism and the risk of breast cancer, prostate cancer and colon cancer, rather than colorectal cancer, lung cancer, and ovarian cancer." (PMID 23951231, 2013). "Studies have shown that in the presence of long non-coding RNA (lncRNA) MIR100HG, hnRNPA2B1 interacts with TCF7L2 in an m6A modification-dependent manner, maintaining the stability of TCF7L2 mRNA and thereby regulating the transcriptional activity of Wnt signal pathway in colorectal cancer." (PMID 40770637, 2025). "In colorectal cancer cells, TSA induces the inhibition of HDAC10 as well as HDAC6, and subsequently attenuates the Wnt pathway by the deletion of the Wnt signaling pathway-associated factor TCF7L2 in a proteasome-dependent way, which suppresses cell proliferation in vitro." (PMID 33997894, 2021).
colorectal cancer (continued). "We found that rs11954856 in the APC gene was associated with colorectal cancer and could increase the expression levels of APC, β-catenin, TCF7L1, TCF7L2 and LEF1 genes in the pathway in the CRC patients, demonstrating the involvement of APC in the pathological processes leading to CRC." (PMID 29050326, 2017). "This complex plays a crucial role in activating Wnt signaling-induced proliferation in colorectal cancer and leukemia stem cells, with TNIK also responsible for phosphorylating TCF4/TCF7L2 (transcription factor-7 like 2)." (PMID 38264262, 2023). "However, the possibility that CRC cells quite often may not be strictly dependent on β-CATENIN or TCF7L2 and that the two factors do not necessarily cooperate in gene regulation call into question the broad suitability of the β-CATENIN/TCF7L2 complex as target for treating colorectal cancer." (PMID 36609428, 2023). "In colorectal cancer, inhibited HDAC10 expression promotes cell apoptosis by depleting transcription factor 7 like 2 (TCF7L2), which attenuates the Wnt pathway." (PMID 33997894, 2021). "Inactivation of the adenomatous polyposis coli (APC) tumor suppressor gene leads to formation of β-catenin/TCF7L2 complexes, constitutive activation of the WNT pathway and eventually colorectal cancer." (PMID 19895682, 2009). "The present study describes another mode of crosstalk between the VDR and β-catenin pathways by demonstrating that TCF7L2/TCF-4, itself, is regulated by VDR/1,25(OH)2D3 in human colorectal cancer cell lines and likely in the mammary gland as well." (PMID 19924301, 2009). "Three-fourths of colorectal cancers possessed APC alterations and about one in four of these cases possessed also concomitant alterations in other genes of the WNT/β-catenin/APC pathway, including RNF43, CTNNB1, and TCF7L2." (PMID 40061138, 2025). "Among these, the largest reduction in stability is observed for the TCF7L2/TCF-4 tumour suppressor (more than 2 PSI units) that regulates the WNT signalling pathway and transactivates downstream target genes involved in the progression of colorectal cancer." (PMID 40276932, 2025). "APC-mutant HT29 and β-catenin–mutant HCT116 colorectal cancer cells with or without TCF7L2 knockout were obtained from the Hecht group (Albert Ludwigs University of Freiburg), and xenograft tumors were generated." (PMID 38488003, 2024). "For example, a MIR100HG/hnRNPA2B1/TCF7L2 feedback loop may be activated by the miRNA-host gene lncRNA MIR100HG, a powerful inducer of epithelial-to-mesenchymal transition in colorectal cancer, and may help explain cetuximab resistance and metastasis." (PMID 37632832, 2023). "TCF7L2 could bind to the promoter of PPARD and increase its expression in human colorectal cancer (CRC) cells." (PMID 26599230, 2015). "Finally, it is worth pointing out that CELF4, TCF7L2, FTO, RUNX1, RUNX3, and CTNNB1 have all been reported to be involved in the etiology of colorectal cancer." (PMID 23626757, 2013). "Accordingly, TCF7L2 silencing leads to genome-wide changes in chromatin architecture and enhancer-promoter interactions in pancreatic and colon cancer cells, whilst TCF-bound Wnt responsive enhancers regulate chromatin looping and activation of the Myc gene in colorectal cancer." (PMID 35709096, 2022). "In line with our observation, it has been reported that in the absence of distinct TCF7L2 variants the regulation of common TCF/LEF target genes such as cyclin D1, c-myc, MMP7 and c-jun is not detectable in renal cell carcinoma and colorectal cancer cell lines." (PMID 21281469, 2011).
colorectal cancer (continued). "It was discovered that colorectal cancers possessed significant differences in their genomic profile dependent on whether the WNT/β-catenin/APC pathway was activated through alterations in APC or through alterations in three alternative genes of the pathway, RNF43, CTNNB1, and TCF7L2." (PMID 40061138, 2025). "In colorectal cancer, the absence of TCF7L2 could promote tumor metastasis." (PMID 39060928, 2024). "Colorectal cancers with alterations in RNF43, CTNNB1, and TCF7L2 without APC alterations presented more commonly MSI and a high TMB." (PMID 40061138, 2025).
breast cancer (57 papers, 2006 to 2026). A primary or metastatic malignant neoplasm involving the breast. "The TCF7L2 gene was reported to be linked with the risk and development of breast cancer and heart diseases." (PMID 38585634, 2024). "Specifically, in breast cancer, these TCF7L2 variants (rs12255372 and rs7903146) shown results contradictories regards to cancer susceptibility." (PMID 35996498, 2022). "Comparative analysis of the AXIN2 and TCF7L2 variants in breast cancer patients and the control group showed significant differences." (PMID 35996498, 2022). "It has been described that genetic alterations in Wnt pathway components, such as APC, β-catenin, AXIN2, and TCF7L2 are implicated in colorectal, melanoma, gastric, hepatocellular, and breast cancer." (PMID 35996498, 2022). "For the variants rs7903146 (C > T) and rs12255372 (G > T) of the TCF7L2 gene, various studies have been conducted in colorectal, prostate, lung, and breast cancer." (PMID 35996498, 2022). "In conclusion, our study shows that the C/T and T/T genotypes of the AXIN2 rs2240308 variant and the TCF7L2 rs7903146 C/T and rs12255372 T/T genotypes are linked to breast cancer." (PMID 35996498, 2022). "Genotype, allele and haplotype frequencies of the AXIN2 and TCF7L2 polymorphisms in the breast cancer patients and control group." (PMID 35996498, 2022). "Regarding the TCF7L2 variants, we observed significant differences when comparing the demographic and clinicopathological characteristics between the breast cancer group and the control group." (PMID 35996498, 2022). "Variants in AXIN2 and TCF7L2 in the Wnt-β catenin pathway have been associated with different types of cancer; however, little is known about its role in breast cancer." (PMID 35996498, 2022). "Their results showed a significant association of genetic variants including AXIN2 rs3923087, β-catenin rs4135385, DKK3 rs6485350, SFRP3 rs7775 and TCF7L2 rs12255372 with breast cancer risk in the population." (PMID 34452579, 2021). "Here, we revealed that rs10514231 affects breast cancer risk by altering ATP6AP1L expression through a functional interaction with TCF7L2." (PMID 34359652, 2021). "Our further systematic mechanical study focusing on the rs10514231 site revealed that the variation affected ATP6AP1L gene expression by altering the chromatin binding of TCF7L2 to the therein regulatory element and led to breast cancer susceptibility." (PMID 34359652, 2021). "Another seven genes (CDH13, CDH7, CTNNA2, ERBB4, GRIK1, PCDH15, and TCF7L2) were reported as associated with the breast cancer by recent GWA studies." (PMID 28615668, 2017). "In this study, three polymorphisms of TCF7L2 (rs1225404, rs7003146, and rs7903146) were genotyped in 458 patients with breast cancer and 500 healthy controls using the Sequenom MassARRAY-iPLEX system." (PMID 27738320, 2016). "This study was conducted to establish the relationship between TCF7L2 polymorphisms (rs1225404, rs7003146, and rs7903146) and clinical features and risk of breast cancer in Northwest Chinese Han women." (PMID 27738320, 2016). "Loci 1q32 and TCF7L2 at 10q25.3 were associated with breast cancer risk, and two loci at 4q32.2 and 17q21.31 were associated with ovarian cancer risk." (PMID 23544013, 2013). "TCF7L2 is a component of Wnt/β-catenin signaling pathway which is implicated in several human cancers including breast cancers." (PMID 23516639, 2013). "It was noted that the minor allele (T) homozygotes for the TCF7L2 rs12255372 conferred 3.8 fold reduced risk for the development of breast cancers compared to women having major allele (G) homozygosity (OR, 0.264; CI, 0.093–0.750)." (PMID 23516639, 2013). "We observed statistically significant association of SNPs in β-catenin (rs4135385), AXIN2 (rs3923087), DKK3 (rs6485350), SFRP3 (rs7775) and TCF7L2 (rs12255372) genes with breast cancer risk." (PMID 23516639, 2013). "Genetic variants in AXIN2, DKK3, SFRP3 and TCF7L2 were associated with reduced risk of breast cancer." (PMID 23516639, 2013).